FTL (ferritin light chain)
Diseases named in the same sentence as FTL in open-access papers (continued):
Sharing a sentence is not in itself a finding about the gene and the disease.
hyperferritinemia-cataract syndrome (11 papers, 2010 to 2025). "Hyperferritinemia/cataract syndrome (HHCS) is caused by mutations (e.g. NM_000146.4:c.-164C > T) in the IRE in the 5′UTR of the L-ferritin (FTL) gene, preventing interaction with the IRPs and leading to dysregulated high levels of L-ferritin production." (PMID 40610610, 2025). "Heterozygous variants in the FTL gene (OMIM 134790) cause hyperferritinemia cataract syndrome (OMIM 60886) and neurodegeneration with brain iron accumulation type 3 (OMIM 606159)." (PMID 31835360, 2019). "We identify four SNPs in the 5′ UTR of the FTL (ferritin light chain) gene that significantly affect the RNA structural ensemble and that are associated with Hyperferritinemia Cataract Syndrome." (PMID 20808897, 2010). "A majority of the known SNPs associated with Hyperferritinemia Cataract Syndrome occur in the 5′ UTR of FTL, suggesting that the UTR is central in the regulation of the gene." (PMID 20808897, 2010). "In humans, mutations in the iron storage protein FTL (ferritin, light polypeptide) and the iron exporter SLC40A1 (solute carrier family 40 [iron-regulated transporter], member 1) lead to hyperferritinemia-cataract syndrome (OMIM #600886)." (PMID 27141993, 2016).
breast carcinoma (10 papers, 2017 to 2024). "Macrophages associated with breast cancer express high levels of ferritin light chain that promotes the M2 macrophage phenotype and fosters a pro-tumor environment in breast cancer by secreting ferritin iron into the stroma." (PMID 33986740, 2021). "FTL increase in cancer lesions was potentially due to the contribution of cancer-associated macrophages secreting ferritin, particularly in response to pro-inflammatory cytokines, but also that extracellular ferritin stimulates the proliferation of breast cancer cells." (PMID 28216608, 2017). "Another example is FTL, which was predicted by our SHAP value to be up-regulated in the high-risk cancer group, was also reported to promote breast cancer cell proliferation validated by knockout experiments." (PMID 38741230, 2024). "On the contrary, ferritin was evaluated by means of western blot in breast cancer cell lines, and results showed that FTL level was significantly elevated in mesenchymal phenotype cell lines compared with epithelial phenotype." (PMID 32677981, 2020). "Previous studies demonstrated that FTL was participate in chemo-resistance of human breast cancer cells and colorectal cancer and inhibition of FTL induced sensitivity of cells to chemotherapy agents." (PMID 32677981, 2020). "In breast cancer, both high levels of FTH and FTL have been suggested to be associated with poor outcome." (PMID 28837569, 2017). "Our data showed that LASS2 overexpression promotes iron uptake by upregulating TFRC expression in thyroid and breast cancer cell lines while simultaneously reducing iron storage by downregulating FTL and FTH expression, thereby elevating labile iron, which further confers ferroptosis sensitivity." (PMID 38419028, 2024). "In addition to TFR1, targeting downregulation of ferritin light chain (FTL) protein by miR-133a increased sensitivity of breast cancer cells to chemotherapy drugs." (PMID 36324180, 2022). "While this has not been observed for FTL yet, it has been reported, that co-targeting of BRD4 and RAC1 disrupts the MYC/G9a axis and enhances the expression of FTH1 in breast cancer cells." (PMID 36231049, 2022).
colorectal cancer (9 papers, 2020 to 2025). A primary or metastatic malignant neoplasm that affects the colon or rectum. "Evidence suggests that HSPA4, HSP90AB1, DNTM1, RPS27, FTL, NCL, A2M are implicated in the pathogenesis and progression of colorectal cancer, positioning them as potential prognostic biomarkers for the onset of metastasis." (PMID 41319168, 2025). "Recent study reported that WTX deficiency inhibits ferroptosis in colorectal cancer cell hematogenous metastasis by inhibiting ubiquitination and degradation of SLC7A11 and FTL." (PMID 40109379, 2025). "Ferritin Light Chain (FTL) completes with long noncoding RNA to regulate chemoresistance and metastasis of colorectal cancer, which was a leading cause of cancer deaths." (PMID 35057823, 2022). "Nevertheless, apart from two studies showing that FTL is elevated in GBM and colorectal cancer, little is known about the expressions of FTL and FTH1 in cancer." (PMID 33864445, 2021). "Correlations between FTL protein level and poor prognosis have been identified in node-negative breast cancer and colorectal cancer, but these findings were not confirmed in our study." (PMID 33864445, 2021).
hepatocellular carcinoma (9 papers, 2018 to 2024). A malignant tumor that arises from hepatocytes. "Indeed, higher expression of the FTL ferroptosis regulator, is associated with a poorer prognosis in hepatocellular carcinoma." (PMID 38049632, 2023). "FTH1,FTL is highly expressed in hepatocellular carcinoma cells and hepatocellular carcinoma tissues." (PMID 37555866, 2023). "The combination of artesunate and hepatocellular carcinoma advanced first-line drug sorafenib induces oxidative stress and ferritinophagy in hepatocellular carcinoma cells and promotes lysosome-dependent FTL degradation to improve the efficacy of single drug." (PMID 38110359, 2023). "We found that PPT1 and FTL were highly expressed in hepatocellular carcinoma cell lines, while DAB2 and SAT1 were highly expressed in human hepatocytes." (PMID 37693905, 2023). "Immunohistochemistry revealed that FTL is abundantly expressed in hepatocellular cancer tissues." (PMID 37354485, 2023). "On the other hand, FTL and hepatocellular carcinoma have been less studied." (PMID 37354485, 2023). "Therefore, we chose FTL for the next step of our study, and immunohistochemistry and the TCGA database verified that FTL is substantially expressed in hepatocellular carcinoma tissues." (PMID 37354485, 2023). "FTL is an independent prognostic variable in HCC patients and the knockdown of FTL can affect the biological behavior of hepatocellular carcinoma cells." (PMID 37354485, 2023). "It is less clear whether or how NFE2L2 influences FTL expression, as NFE2L2 does not seem to regulate FTL mRNA levels in hepatoma cells and negatively regulates FTL mRNA and protein levels in human cells and in mice." (PMID 39025451, 2024).
cataract (8 papers, 2010 to 2025). Partial or complete opacity of the crystalline lens of one or both eyes that decreases visual acuity and eventually results in blindness. "These cataracts are caused by mutations in the ferritin light chain (FTL) on chromosome 19." (PMID 22219628, 2011). "Beyond this case, we provide a comprehensive review of HHCS, including molecular mechanisms, an updated overview of reported FTL mutations, and ophthalmological features that distinguish HHCS cataracts from other congenital cataracts." (PMID 41300832, 2025). "Variations at IRE in the transcripts for ferritin light chain (FTL) gene cause hereditary hyperferritinemia – cataract syndrome (HHCS) with increased serum ferritin levels and early-onset cataracts." (PMID 32951567, 2021). "This autosomal dominant syndrome, that typically presents with juvenile bilateral cataracts, was first described in 1995 and has an increasing number of recognized molecular defects within a regulatory region of the L-ferritin gene (FTL)." (PMID 21936912, 2011). "Finally, variations in at least eight genes underlying genetic forms of cataract (EPHA2, GJA8, GALT, SLC16A12, HSF4, GALK1, FTL, and CRYAA), and at least 10 other diverse genes have been associated to varying degrees with age-related cataract." (PMID 21042563, 2010).
iron overload (8 papers, 2013 to 2025). "Based on these findings, we suggest that Nrf2 ablation induces depression susceptibility by modulating FtL, Tf and TfR in neurons, leading to aggravated iron overload." (PMID 37735410, 2023). "Moreover, four other genetic forms of hemochromatosis (HFE2A, HFE2B, HFE3, HFE4) were excluded, since they are associated with iron overload linked to genes other than FTL (OMIM ID: 608374, 606464, 604720, 604653)." (PMID 23592921, 2013). "Investigations of TF, FTL, PCBP1 and VDAC3 and their different specificities in terms of their roles in iron metabolism, independent of lipid-lowering treatment actions, may also be of high interest in the treatment of iron overload and deficiency." (PMID 35181730, 2022). "Using the expression level of FTH1 and FTL to reflect iron overload is not a specific indicator for iron overload in leukemia and has limitation." (PMID 40881683, 2025).
lung carcinoma (7 papers, 2012 to 2025). "MPE collected from lung cancer patients with pleural metastasis stimulated the expressions of GPX4, FTL, and NUPR1, whereas decreased the expression of ACSL4 in both A549 and H1975 cells." (PMID 37649596, 2023). "In cluster 6, the upregulated FTL (65 fold in our study) and ALDOA (7 fold in our study) were regulated by hypoxia inducible factor (HIF) during lung cancer." (PMID 23122428, 2012). "Moreover, iron transportation-related proteins such as TFR, FTL, and FTH were found to be upregulated in lung cancer." (PMID 36814470, 2023). "Zhang’s group selected a panel of five urinary molecules (ferritin light chain, mitogen-Activated Protein Kinase 1 Interacting Protein 1-Like, fibrinogen Beta Chain, two Member RAS Oncogene Family, RAB33B and RAB15) as a predictive model to differentiate lung cancer from healthy lung tissue." (PMID 33923502, 2021). "sEVs of hypoxic melanoma, squamous skin carcinoma and lung cancer cells are loaded with immunosuppressive proteins like colony-stimulating factor 1 (CSF-1), C-C motif chemokine 2 (CCL2), ferritin heavy chain (FTH), ferritin light chain (FTL) and TGF-β as well as the miRNA let-7a." (PMID 32709110, 2020).
Sepsis (7 papers, 2018 to 2024). Sepsis is defined as life-threatening organ dysfunction caused by a dysregulated host response to infection. "In this study, we used murine models of sepsis to interrogate the role of FtL in the pathophysiology of sepsis-associated acute kidney injury (SA-AKI)." (PMID 38779751, 2024). "As McCullough K reported, serum ferritin and FtL can prevent hyperinflammation during sepsis, which is associated with the decrease of NF-κB activation." (PMID 36523541, 2022). "We designed this study to test the hypothesis that loss of myeloid FtL and subsequently, circulating FtL will exacerbate the sepsis-induced inflammatory response and worsen SA-AKI." (PMID 38779751, 2024). "We attempted to interrogate our myeloid FtL knockout model through broad exposure to multiple sepsis models, but consistently demonstrated that myeloid FtL deletion did not influence kidney injury." (PMID 38779751, 2024). "Ferritin plays a critical role in regulating the inflammatory response through the biological activity of FtH and FtL in murine models of sepsis." (PMID 38779751, 2024). "We previously showed the myeloid deletion of FtH results in a compensatory increase in FtL and is associated with reduced circulating cytokines and decreased rates of SA-AKI in animal sepsis models." (PMID 38779751, 2024). "We generated a novel myeloid-specific FtL knockout mouse (FtLLysM–/–) and induced sepsis via cecal ligation and puncture or lipopolysaccharide endotoxemia." (PMID 38779751, 2024). "Despite these findings, direct evidence for FtL as an anti-inflammatory mediator in sepsis remains elusive." (PMID 38779751, 2024). "Results also demonstrated that the protective effects of FtL during sepsis are attributed to its inhibitory actions against the activation of the NF-κB pathway." (PMID 31234273, 2019). "Taken together these data suggest that FtL diminishes NF-κB activation and downstream inflammatory response and confers resistance to sepsis." (PMID 30804939, 2019). "Taken together, while FtL overexpression was shown to be protective against sepsis, the loss of FtL did not influence sepsis pathogenesis." (PMID 38779751, 2024). "The loss of FtL did not impact sepsis-mediated activation of NF-κB or HIF-1a signaling, key inflammatory pathways associated with dysregulated host response." (PMID 38779751, 2024). "Despite myeloid FtL deletion, we observed increased bulk kidney FtL expression in both FtLfl/fl and FtLLysM–/– mice 24 h post-sepsis compared with quiescence, which could be attributed to kidney parenchymal cell FtL expression." (PMID 38779751, 2024). "Current evidence suggests FtL overexpression, in the setting of sepsis, may attenuate the severity of proinflammatory pathways and protect against SA-AKI." (PMID 38779751, 2024). "However, we recently reported that FtL possesses immunomodulatory properties and high levels of circulating FtL conferred protection against mortality and end-organ damage in a model of sepsis." (PMID 35955444, 2022). "The effect of FtH and light FtL on sepsis was discussed previously." (PMID 36523541, 2022). "Our in vitro and in vivo FtL administration studies indicate that prior exposure to FtL provides significant resistance to the septic process by mitigating overproduction of cytokines involved in the pathogenesis of sepsis." (PMID 30804939, 2019). "To investigate whether increased serum ferritin levels offered resistance to sepsis, we administered recombinant FtL to FtHfl/fl mice, performed CLP surgery and measured the levels of inflammatory cytokines in the serum after 24 h." (PMID 30804939, 2019). "Since the major source of circulating ferritin is FtL, we postulated that this elevated serum ferritin may play a role in inflammation during sepsis." (PMID 30804939, 2019). "We further recapitulated these findings using a mild form of sepsis (LPS administered at 2.5 mg/kg), suggesting that FtL deletion did not affect sepsis pathogenesis." (PMID 38779751, 2024).
Sepsis (continued). "Myeloid-specific FtL deletion does not alter the systemic production of proinflammatory cytokines or early markers of acute kidney injury in mice challenged with sepsis." (PMID 38779751, 2024). "However, our findings with two different doses of LPS with varying severity of inflammation and kidney injury further confirm that myeloid FtL deletion does not affect sepsis pathogenesis." (PMID 38779751, 2024). "Therefore, in a myeloid-specific FtL knockout model, we hypothesize that selective deletion of FtL will exacerbate hyperinflammatory pathways, leading to increased systemic proinflammatory cytokines and more severe patterns of SA-AKI in mice challenged with sepsis." (PMID 38779751, 2024).
lung adenocarcinoma (5 papers, 2021 to 2026). A carcinoma that arises from the lung and is characterized by the presence of malignant glandular epithelial cells. "Transcriptional inhibition of FTL has also been reported to increase the sensitivity of cancer cells to ferroptosis in lung adenocarcinoma." (PMID 35651950, 2022). "Likewise, repression of FtL increases the propensity for ferroptosis in a lung adenocarcinoma model, indicating a potential counterregulatory role for FtL in balancing the proinflammatory activity of FtH." (PMID 38779751, 2024). "In lung adenocarcinoma, YAP diminished intracellular iron levels by promoting FTL transcription through transcription factor CP2 (TRCP2)." (PMID 35979359, 2022).
melanoma (5 papers, 2020 to 2025). A malignant, usually aggressive tumor composed of atypical, neoplastic melanocytes. "In melanoma samples, high FTL was detected in primary and metastatic lesions by immunohistochemistry but was exclusively cytoplasmic." (PMID 32328462, 2020). "Analysis of bone tissues using qPCR showed that melanoma metastasis caused degradation of ferritin light chain 1 (Ftl1), while ferritin heavy chain 1 (Fth1) was not affected." (PMID 39814705, 2025). "In melanoma cells FTL is necessary to resist oxidative stress-induced apoptosis." (PMID 32328462, 2020). "The highest correlations observed with HMOX-1 in patients with melanoma were with FZD2 (rho = 0.54), KEAP1 (rho = 0.59), MAPK13 (rho = 0.68), the “ferroptosis” gene FTL (rho = 0.58), and CHUK (rho = −0.50)." (PMID 35053476, 2022). "A core group of differentially expressed genes (FTH1, FTL, HSPA8, HSP90AA1, and HSP90B1) was recurrently identified within significantly enriched pathways across TCGA melanoma samples and clinical cohorts." (PMID 32296058, 2020). "In two separate studies downregulation of FTL with an antisense construct and FTH1 with shRNA in melanoma cells inhibited proliferation and invasion in vitro and tumor growth in vivo." (PMID 32328462, 2020).
Alzheimer disease (4 papers, 2018 to 2025). A progressive, neurodegenerative disease characterized by loss of function and death of nerve cells in several areas of the brain leading to loss of cognitive function such as memory and language. "In this specific study we identified dystrophic FTL+Iba1+TMEM119−P2RY12−-microglia to be significantly more present in Alzheimer’s disease patient, and to be the predominant Aβ-plaque infiltrating microglia cluster." (PMID 33597025, 2021). "In addition, there was a significant decrease in transcripts for ferritin light chain (FTL) and ferritin heavy chain (FTH1) in the cerebellum of patients with Alzheimer’s disease, which also had a significant reduction in ferroportin." (PMID 38667304, 2024).
anemia (4 papers, 2020 to 2026). A reduction in the number of red blood cells, the amount of hemoglobin, and/or the volume of packed red blood cells. "In keeping with their iron-delivery and anti-ferroptosis roles, we also explored associations of FTH1 and FTL with anemia and isoprostanes (specific markers of in vivo oxidative stress) in PWH." (PMID 39334701, 2024).
colon cancer (4 papers, 2019 to 2023). "FTL is up-regulated via the Linc00467/miR-133b pathway, resulting in cell resistance to 5-FU and promoting colon cancer metastasis." (PMID 36910614, 2023). "On the other hand, the expression of FTL in colon cancer increased, which can modulate the sensitivity of colon cancer to chemotherapy." (PMID 36910614, 2023).
COVID-19 (4 papers, 2022 to 2026). A disease caused by infection with severe acute respiratory syndrome coronavirus 2. "Despite the high basal level of FTL in macrophages, we found FTL signals outside of macrophage markers (CD68 and CD11c) in severe COVID-19 lungs, suggesting that other alveolar cell types were involved in FTL upregulation." (PMID 38769293, 2024). "We evaluated the expression of TfR1 and ferritin light chain (FTL) in COVID-19 lungs with severe and mild pathology, obtained from lung explant/biopsy of severe and recovered COVID-19 patients, respectively." (PMID 38769293, 2024). "Single-cell and bulk transcriptomic profiling of severe COVID-19 lungs further reveal upregulation of iron-regulatory transcripts (FTL, FTH1, TFRC) in pulmonary epithelial cells and macrophages, supporting a picture of tissue-specific iron dysregulation and enhanced ferroptotic vulnerability." (PMID 41516398, 2026). "We found that native serum ferritin protein in COVID-19 patients was composed of approximately 75.4 ± 10.35% FTL and 24.6 ± 10.35% FTH1 (SupplementaryFigure 10B), and that in individuals with ARDS who died had a trend for higher levels of FTL when compared to patients with ARDS who survived." (PMID 41542049, 2026). "We show for the first time that while serum ferritin in COVID-19 contained both FTH1 and FTL, it is predominantly composed of FTL." (PMID 41542049, 2026). "We analyzed the transcription of 9 major iron regulatory genes, among which FTL, ferritin heavy chain 1 (FTH1), and TfR1 are the most elevated genes in COVID-19 lung." (PMID 38769293, 2024).